MACROH2A1 (macroH2A.1 histone)
Diseases named in the same sentence as MACROH2A1 in open-access papers (continued):
Sharing a sentence is not in itself a finding about the gene and the disease.
tumor (continued). "Using two CRC cell lines, they also showed that siRNA-mediated macroH2A1 silencing led to decreased tumor proliferation after rescue of p16 expression, suggesting that macroH2A1 could be considered an oncoprotein." (PMID 31096699, 2019). "Moreover, macroH2A1.1 downregulation favours metastasis and correlates with decreased patient survival and tumour recurrence, as shown in lung cancer." (PMID 25003966, 2014). "The macroH2A1.1 isoform is expressed at high levels in cells that undergo senescence, a debated anticancer mechanism, suggesting that macroH2A1.1 may be a useful biomarker of senescent tumor cells." (PMID 34440260, 2021). "Thus, its putative role might be tumor model-dependent, since MacroH2A1.1 might have an activating or repressive function depending on external cellular signals." (PMID 31164793, 2019). "For instance, H-Ras, CD44, PXN-AS1, macroH2A1, etc., are important tumor-related factors; therefore, the dysregulation of DDX5/DDX17 action is closely related to tumorigenesis and tumor progression." (PMID 35992805, 2022). "Next, to deeply understand the role of macroH2A1 in tumor differentiation, we inoculated female athymic nude mice with control (CTL), macroH2A1 knock-down (KD), or macroH2A1.1 or macroH2A1.2 over-expressing HepG2 cells." (PMID 31096699, 2019). "From feature analysis we concluded that collagens, MACROH2A1, HPF1, COL4A3, TBB2C, actin, and H2B are promising targets for the understanding of tumor progression and development of distant metastases, and consequently inspiring novel treatment of PDAC metastatic lesions." (PMID 35956764, 2022). "Finally, compared to macroH2A1 KD Huh-7 cells, FAK KD cells exhibited a significant reduction (p < 0.01) in the mRNA levels of tumor-promoting genes CCL2, EGF, BAX, KRT19, EGFR, NOTCH1, ABL1, and SMAD3." (PMID 33182805, 2020). "Therefore, we sought to determine if altered macroH2A1 isoform (macroH2A1.1 and macroH2A1.2) levels in HCC patient tissue samples correlate with altered frequency of tumor resident senescent cells." (PMID 31903159, 2020). "Alternative splicing of macroH2A1 isoforms, however, does not occur in all tumor types; it seems irrelevant in HCC, for instance, where down-regulation of both macroH2A1.1 and macroH2A1.2 occurs at the mRNA and protein levels." (PMID 31096699, 2019). "Indeed, PIN lesions disclosed higher MacroH2A1.1 transcript levels than PCa, in cases in which PIN and matched tumor lesions from the same prostatectomy specimens were available." (PMID 31164793, 2019). "As expression of macroH2A1.1 seems to be correlated with EMT and unfavorable behavior in untreated TNBC patients, it is tempting to suggest macroH2A1.1 expression levels as an early biomarker of tumor genesis." (PMID 24911873, 2014). "Alternative splicing of macroH2A1 isoforms does not occur in all tumor types; it seems irrelevant in HCC, for instance, where we observed a downregulation of both macroH2A1.1 and macroH2A1.2 at the mRNA and at the protein level." (PMID 29206173, 2017).
infection (3 papers, 2020 to 2023). The state of being infected such as from the introduction of a foreign agent such as serum, vaccine, antigenic substance or organism. "We used k-means clustering during the time course of infection compared with mock to identify patterns of macroH2A1 gain or loss during infection." (PMID 37516914, 2023). "We found that total RNA levels anti-correlate with macroH2A1 presence: clusters 1–3 had an increase in RNA levels, whereas clusters 4–6 had a decrease in RNA levels over the course of infection." (PMID 37516914, 2023). "We then calculated the change in the enrichment of macroH2A1 in these sections across the infection time course." (PMID 37516914, 2023). "Through chromatin profiling during infection, we revealed global redistribution of these marks whereby massive host genomic regions bound by macroH2A1 and H3K27me3 correlate with decreased host transcription in active compartments." (PMID 37516914, 2023). "Furthermore, these data support a model in which macroH2A1 supports chromatin rearrangement induced during infection." (PMID 37516914, 2023). "We hypothesized that macroH2A1 and H3K27me3 are deposited at specific genomic loci on the host genome during infection to promote the formation of heterochromatin." (PMID 37516914, 2023). "We, therefore, hypothesized that macroH2A1 was critical for the infection-induced formation of open space at heterochromatin boundaries." (PMID 37516914, 2023). "The time course comparison revealed that in clusters 5 and 6, where we found an increase in macroH2A1 and H3K27me3 presence during infection, the 4sU-labeled RNA decreased at 8 hpi compared with mock, indicating that the gain in heterochromatin correlates with a reduction in active transcription." (PMID 37516914, 2023). "Control cells (CTL) were infected with a bicistronic construct expressing green fluorescent protein (GFP) and a scramble shRNA, while silencing of macroH2A1 was achieved through lentiviral infection of a bicistronic construct containing shRNA against macroH2A1 and a GFP cassette (knock-down, KD)." (PMID 32401230, 2020). "Our finding that macroH2A1-defined clusters exhibit decreases in transcription upon heat shock and salt stress suggests that global changes to heterochromatin are likely a consequence of the cell’s stress response to infection that HSV-1 exploits to access the INM." (PMID 37516914, 2023). "Thus, the deposition of macroH2A1 is not directly affecting the expression of specific genes that would be pro- or anti-viral, but rather it is likely that these changes in transcription are a result of the stress response to infection." (PMID 37516914, 2023).
hematologic malignancies (2 papers, 2019 to 2024). "Lacking macroH2A1.1 induces the development of hematologic malignancies." (PMID 39199381, 2024).
metabolic disorder (1 paper, 2010). "Furthermore, male mice, which are not prone to the metabolic disorder, had a reduced level of macroH2A1 incorporated into the Tbg promoter." (PMID 20359320, 2010).
MACROH2A1 also shares sentences with these, for which no sentence is quoted: pancreatic cancer (3 papers); uveal melanoma (3); anaemia (2); cervical cancer (2); acute myeloid leukaemia (1); Alzheimer disease (1); Anxiety (1); anxiety disorder (1); astrocytoma (1); bladder tumor (1); breast tumors (1); colorectal cancer (1); Deep Venous Thrombosis (1); glioblastoma (1); Glucose intolerance (1); Insulin resistance (1); invasive carcinoma (1); liver disease (1); lung adenoma (1); memory impairment (1); metabolic syndrome (1); neuroblastoma (1); non-alcoholic steatohepatitis (1); ovarian carcinoma (1); pancreatic ductal adenocarcinoma (1); Parkinson disease (1); primary effusion lymphoma (1); prostate (1); schizophrenia (1); skin cancer (1).
A further 3 diseases each share a sentence with MACROH2A1 in 1 paper.